APLN (apelin)
Diseases named in the same sentence as APLN in open-access papers (continued):
Sharing a sentence is not in itself a finding about the gene and the disease.
tumor (continued). "APLN is activated by VEGF signaling and hypoxia-responsive elements in the APLN promoter, stimulates angiogenic sprouting, and plays a necessary and sufficient role in tumor angiogenesis." (PMID 36588901, 2022). "Since cachexia in this tumor model can be observed only in slow growing tumors, different numbers of FC1199 cells were transplanted orthotopically in the pancreas of C57BL/6 mice and apelin mRNA expression in tumors compared." (PMID 35406586, 2022). "Again, apelin did not appear to have any effect on body or MWL or on tumor growth, confirming that regardless of the route of administration, activation of this pathway does not preserve muscle size." (PMID 35406586, 2022). "In some mouse tumor models, it has been reported that Apelin induces tumor growth; however, survival rate in those tumor models was not evaluated." (PMID 34234274, 2021). "Treating experimental GBM models with Apelin-F13A had anti-angiogenic and anti-invasive effects and reduced tumor volume but did not lead to a decrease in TAM." (PMID 34359800, 2021). "Compared with patients with low apelin levels and those with weak or negative apelin staining, patients with high tumor apelin levels showed a significantly shorter OS." (PMID 33912466, 2021). "Using adult APLN-creER and APLNR-creER transgenic mouse models, it was confirmed that APLN/APLNR expression is low in adult physiology but it is upregulated in ECs during tumor angiogenesis." (PMID 34359800, 2021). "In pathological conditions, Apelin has been identified as a tumor endothelium-specific gene, not expressed by normal endothelium." (PMID 34234274, 2021). "This excludes the possibility that Apelin exerts a direct effect on immune cells responding to the tumor." (PMID 34234274, 2021). "Several papers studied the exact role of apelin in primary tumors and tumor angiogenesis, but there is a lack of research related to the role of apelin in the disseminating process." (PMID 33707612, 2021). "Comparing with WT mice, larger numbers of vessels with narrower diameters were observed in tumors of Apelin knockout mice and lack of Apelin enhanced tumor hypoxia." (PMID 34234274, 2021). "However, when APLN expression was fully depleted as in U87AKDAPLNKO xenografts, only 50% of tumor cell implantation led to successful tumor growth." (PMID 32545380, 2020). "In summary, we found that the absence of APLN expression from the tumor microenvironment showed a beneficial effect on the survival of GBM-bearing mice." (PMID 32545380, 2020). "Interestingly, in two independent experiments, the infusion of apelin facilitated 4T1 TNBC growth in lean mice, leading to significantly bigger tumour sizes than in vehicle‐treated animals." (PMID 32681609, 2020). "We found that apelin infusion increases tyrosine phosphorylation of the key angiogenic marker vascular endothelial growth factor receptor 1 (VEGFR1), thereby suggesting an increased tumour neoangiogenesis." (PMID 32681609, 2020). "Recently, APLN receptor (APLNR) was considered to be an essential gene for tumor immunotherapy, which can modulate the function of CD8+T cells, but the immunological effects of the APLN/APLNR axis in ccRCC remain unknown." (PMID 33324682, 2020). "High cytoplasmic immunoreactivity of apelin was present in the tumor cells but not in the surrounding stroma." (PMID 31070305, 2019). "In this study, we show that depriving the tumor of the angiogenic molecule Apelin reduces tumor growth without increasing metastasis." (PMID 31267692, 2019). "Therefore, in this study we examined mRNA and the protein level of apelin and its receptor in CRC tumour tissue obtained from surgically treated patients." (PMID 31547096, 2019). "We found that APLN mRNA expression was significantly increased among HCC tumors with alterations in PI3K/Akt or Wnt/β-catenin pathways, an observation that was validated in other tumor types." (PMID 31410213, 2019).
tumor (continued). "Analysis of mRNA expression showed increased levels of apelin in tumor tissue in comparison to non-tumor tissue in CRC individuals (p = 0.0007)." (PMID 31547096, 2019). "Expression of the apelin/APJ system in patients, tumor tissues, or cell lines." (PMID 28484393, 2017). "On the other hand, image analysis data (H-Score) showed a significantly (p=0.01) higher APLN protein expression in tumour tissues from the non-responder patient group compared to the responder group." (PMID 28487489, 2017). "Apelin is known to signal through the G-protein coupled receptor APLNR (also known as APJ), which is reported to be highly expressed throughout the brain and act as paracrine and autocrine factor that supports embryonic and tumour angiogenesis." (PMID 29053791, 2017). "A second limiting factor is that we do not know the distribution of APLN expression throughout the whole tumour." (PMID 28487489, 2017). "Although there is a lack of information regarding the participation of apelin in immune responses, some data support its participation in tumor neovascularization, since apelin promotes the proliferation of endothelial cells." (PMID 25918733, 2015). "Specifically, we found a low positive correlation between APLN and CYR61 (r = 0.16), a stronger correlation between APLNR and CYR61 (r = 0.68), a low correlation between APLNR and RIC8A (r = 0.20), and a moderate correlation between APLNR and TUBA1A (r = 0.58) in tumor patients." (PMID 39962271, 2025). "Molecular factors such as PTPRH, CPNE1, APLN, PLOD1, SPAG4, B7‐H3, and SIK2 have been shown to facilitate carcinogenesis and glycolysis via PI3K/AKT induction, whereas inhibitors of this pathway reduce glycolytic flux, diminish tumor growth, and increase sensitivity to anticancer drugs." (PMID 40740483, 2025). "Research indicates that Apelin can enhance the expression of MMP‐2 through the activation of the PI3K/Akt pathway and FOXO3A, leading to the degradation of the ECM and promoting the motility and migration of vascular smooth muscle cells (VSMCs), which facilitates tumour invasion and metastasis." (PMID 39434201, 2024). "Apelin was identified as a central regulator of endothelium-dependent tumour initiation and maintenance in GBM cells with stem-like properties, and the apelin receptor antagonist, MM54, was used to successfully reduce tumour expansion and lengthen survival in a GBM xenograft mouse model." (PMID 38803685, 2024). "With the advances in cellular and molecular biology, various biomolecules involved in tumor angiogenesis have been identified, such as vascular endothelial growth factor (VEGF), platelet-derived growth factor (PDGF), fibroblast growth factor 2 (FGF-2), chemokines, ephkrine, apelin (APLN)." (PMID 39518052, 2024). "In the Apelin (+) group, pro-inflammatory factors are decreased, while anti-inflammatory factors are heightened.Tumor-derived extracellular vesicles expressing TGF-β also play a significant role in the crosstalk between tumor cells and macrophages in the HNSCC TME." (PMID 38650924, 2024). "However, in the invasive stage, apelin and APJ were co-expressed by tumor cells." (PMID 36142542, 2022). "Our data support apelin as produced only by cachexia-promoting tumors, regardless of tumor types." (PMID 35406586, 2022). "Therefore, given that both the VEGFA and APLN exerted angioplasty effects on the stroma in a paracrine way, the hypoxia-related signaling initiated by the aberrantly accumulated HIF1 in the KIRC tumor can be acknowledged as their shared upstream origin." (PMID 35079698, 2021). "On the basis of these results, we hypothesize that the Apelin-induced CCL8 secreted by ECs provides a chemotactic signal to CD8+ and CD4+ T cells and promotes T cell extravasation from vessels and infiltration into the tumor." (PMID 34234274, 2021). "However, tumor growth in animals infused with [Pyr1]Apelin-13 or saline was not significantly different." (PMID 34234274, 2021).
tumor (continued). "In the current cohort, BMI and tumor apelin did not correlate, suggesting these two parameters might independently affect response to NAC." (PMID 33972642, 2021). "However, we do know that the distribution of macrophages throughout the tumor was not different in the presence or absence of Apelin." (PMID 34234274, 2021). "Third, high circulating apelin could promote tumour growth without affecting tumour apelin expression." (PMID 32681609, 2020). "First, high circulating apelin may not affect tumour growth directly but rather increase tumour apelin expression." (PMID 32681609, 2020). "Therefore, we infused the bioactive apelin-13 peptide into the U87AKDAPLNKO xenograft model and were indeed able to obtain a partial rescue of the tumor neo-vasculature increasing VLD from 766 mm/mm3 (infusion of artificial cerebrospinal fluid; aCSF control) to 2573 mm/mm3." (PMID 32545380, 2020). "Interestingly, the absence of apelin upregulation in the tumor vasculature of APLNKO mice led to smaller tumor volume and a significant extension of the survival time for GBM-bearing mice." (PMID 32545380, 2020). "However, how activation of APLN-APLNR regulates tumorigenesis and tumor progression remains unclear." (PMID 31410213, 2019). "While total immune cell infiltration, as determined by the numbers of CD45+ cells in the tumor, was unchanged, we found a significant decrease of polymorphonuclear myeloid‐derived suppressor cells (PMN‐MDSC) and a significant increase in NK T cells in tumor from Apelin‐depleted mice." (PMID 31267692, 2019). "Therefore, instead of apelin, an antibody against APJ may be more useful for ligating this receptor expressed on tumor ECs." (PMID 23799018, 2013). "Here, we investigated whether apelin-conjugated liposomes can be internalized via APJ in APJ-expressing cells and whether agents encapsulated in these liposomes could be successfully targeted to tumor EC." (PMID 23799018, 2013). "Although the genes in (PRKAA2, GNG7, MYL3, NOS1, ADCY1, PLCB1, MYLK3, and MYLK4) the apelin/APJ signaling axis are found to be downregulated and might not be considered responsible in cdRCC progression, downregulation of GNG7 tells a different story due to its tumor‐suppressive activity." (PMID 40304310, 2025). "Additionally, secondary annotation of vascular ECs indicated that high APJ ECs was more enriched in capillaries, leading us to hypothesize that apelin/APJ might promote the growth and advancement of tumours by facilitating the generation of capillaries within the tumour." (PMID 39434201, 2024). "However, the mechanism by which Apelin alone inhibits tumor growth had not been determined." (PMID 34234274, 2021). "Our finding that the in vivo volume assessed by MRI was smallest when APLN was expressed by the tumor cells, but not by the vessels, might be explained by improved tightness of the neo-vasculature and, consequently, improved function and reduced formation of brain edema." (PMID 32545380, 2020). "Other studies, however, suggest that there is no direct relationship between the apelin/APLNR axis and the degree of tumor malignancy; rather, it depends on the cell type that generates the tumor." (PMID 41515992, 2025). "Unlike apelin, we did not detect APJ in PanIN tumor cells in premalignant lesions in the KC and KPC mouse models." (PMID 36142542, 2022). "Comparison of non-tumor and tumor tissue showed statistically increases of apelin concentration in CRC with p < 0.0001 and the apelin tumour/non-tumour ratio was 1.68." (PMID 31547096, 2019). "Accordingly, pharmacological blockade of apelin, but not the reduction of APLNR expression in GSCs, may also contribute to the reduction of tumour volume observed in this study in vivo, by blocking angiogenesis and depriving tumour cells of the nutrients they require to survive." (PMID 29053791, 2017).
cardiovascular diseases (68 papers, 2012 to 2025). "The broad spectrum of cardioprotective effects associated with the apelin–ELA–APJ system makes it an attractive target in the search for novel therapies for cardiovascular diseases." (PMID 41155377, 2025). "This review will focus on the apelin–APJ signaling system related to age-associated cardiovascular diseases." (PMID 29302260, 2017). "In this review, we discuss the apelin–APJ signal transduction pathway related to age-associated cardiovascular diseases." (PMID 29302260, 2017). "Further studies with greater sample size and robust statistical analysis are necessary in order to better inquire the association between apelin and cardiovascular disease pathogenesis and risk." (PMID 24089668, 2013). "A previous meta-analysis study reported that the apelin/HDL-c, apelin/LDL-c and apelin/TCH ratios could be used as diagnostic markers for cardiovascular diseases." (PMID 40299338, 2025). "Apelin and apela have anti-apoptotic activity in a number of tissues and cells and both apelin and apela have been implicated in cardiac pathophysiology and cardiovascular disease." (PMID 28817612, 2017). "Dysregulation of the apelin/APJ system may be involved in the predisposition to cardiovascular diseases, and enhancing apelin action may have important therapeutic effects." (PMID 22655211, 2012). "In conclusion, this study underscores the potential of therapeutic peptides, particularly Apelin, in targeting cardiovascular disease through their interaction with specific receptors." (PMID 39859178, 2025). "Being a powerful inotrope and effector on fluid homeostasis, Apelin’s role as a target for cardiovascular diseases bears importance." (PMID 41154645, 2025). "Overall, apelin was safe and well tolerated in CKD patients and our data define the translational potential of apelin as a new therapy for CKD and its associated cardiovascular disease." (PMID 39402039, 2024). "Overall, the apelin system offers exciting therapeutic potential for a range of cardiovascular diseases." (PMID 37956047, 2023). "Numerous physiological processes and pathological conditions, such as cardiovascular disease, angiogenesis, energy metabolism, and fluid balance, are influenced by the apelin/APJ system." (PMID 37107553, 2023). "This review will provide an overview of the role of apelin signalling in the (patho)physiology of cardiovascular disease and the potential benefits of apelin treatment." (PMID 37956047, 2023). "This review will discuss current cardiovascular disease targets of the apelin system and future clinical utility of apelin receptor agonism." (PMID 37956047, 2023). "Apelin, the endogenous adipokine, can protect against cardiovascular disease via activating its receptor, APJ." (PMID 37497114, 2023). "APLN and APLNR are regulated by hypoxia, and the APLN–APLNR axis system has a protective effect on cardiovascular diseases." (PMID 36611783, 2023). "APJ receptors share high homology with the Ang II type 1 receptor; thus, apelin was proposed to play a protective role in cardiovascular disease by antagonizing the actions of Ang II." (PMID 37111357, 2023). "The present systematic review and meta-analysis aimed to ascertain if the circulating levels of apelin, as an important regulator of the cardiovascular homeostasis, differ in patients with cardiovascular diseases (CVDs) and controls." (PMID 35913970, 2022). "For patients with cardiovascular disease, increased serum apelin was found in children and adults who were obese compared to the non-obese, especially those consuming a high-fat diet." (PMID 36230579, 2022). "Apelin is responsible for, i.a., cardiovascular function and insulin secretion, and its functional disorders are associated with DM2 and cardiovascular system diseases." (PMID 34684585, 2021). "The apelin/apelin receptor system plays an important role in cardiovascular function, and apelin therapy has beneficial effects in cardiovascular disease." (PMID 33573223, 2021).
cardiovascular diseases (continued). "In conclusion, apelin peptides have protective roles in cardiovascular diseases, however, any potential therapeutic use is impaired by the poor plasma stability of the peptide." (PMID 31882594, 2019). "Forth, although apelin emerges as a novel biomarker against cardiovascular diseases which is a member of the adipose tissue-derived peptides, we did not measure them." (PMID 30872595, 2019). "Based on these beneficial effects, apelin was proposed as a potential therapeutic target in cardiovascular diseases." (PMID 31882594, 2019). "Numerous literature reports have indicated that cardiovascular diseases progress together with the impairment of apelin expression." (PMID 30286717, 2018). "Several studies have demonstrated that apelin can be treated as a biomarker of cardiovascular diseases." (PMID 29875677, 2018). "Apelin, an endogenous ligand for Apelin receptor, acts as a key modulator of cardiovascular diseases." (PMID 29245958, 2017). "Nowadays there are an increasing number of studies assessing apelin in an attempt to clarify its role as a cardiovascular disease (CVD) marker." (PMID 24089668, 2013). "The apelin/angiotensin receptor-like 1 (apelin/APJ) pathway has emerged as an essential novel mediator of cardiovascular disease." (PMID 23226564, 2012). "It is important to recall that apelin is thought to exert a wide range of effects on different organs, and although its role in cardiovascular diseases is well established, its exact effect on endothelial cells has not been clearly defined." (PMID 22927708, 2012). "While adipokines like adiponectin, apelin, and omentin have anti-inflammatory and cardioprotective properties, others like leptin, resistin, and visfatin exert pro-inflammatory effects, contributing to cardiovascular disease." (PMID 40362168, 2025). "The alignment of Apelin’s pharmacological action with its binding affinities for these receptors implies that it could be beneficial in preventing and treating cardiovascular diseases." (PMID 39859178, 2025). "The apelin system is a promising therapeutic target for a range of cardiovascular diseases." (PMID 37956047, 2023). "The precise role of elabela in relation to the apelin signalling pathway in cardiovascular disease remains to be elucidated, particularly whether elabela has distinct physiological, pathophysiological, and pharmacological actions from apelin." (PMID 37956047, 2023). "A meta-analysis of 30 studies revealed a negative association of apelin serum levels with cardiovascular diseases." (PMID 37239123, 2023). "Taken together, the apelin/APJ-targeting therapy may be more effective for cardiovascular disorders with hypoxic conditions." (PMID 37111357, 2023). "Apelin is widely expressed in various organs including heart and vasculature and is the endogenous ligand for the APJ receptor, which has been linked to the pathogenesis of cardiovascular diseases." (PMID 36017090, 2022). "It has been reported that plasma apelin levels are decreased in several cardiovascular diseases." (PMID 35783816, 2022). "Recent studies suggest apelin has multiple protective effects in some cardiovascular diseases." (PMID 35783816, 2022). "Apelin appears to be a promising adipocytokine for cardiovascular diseases (CVDs)." (PMID 36199867, 2022). "Thus, future studies with female rats, various age groups, and appropriate models of cardiovascular disease will be needed to further enhance our understanding of the vasomotor effects of apelin." (PMID 34122102, 2021). "In addition, omega-3 fatty acids supplementation in patients with cardiovascular diseases increased APLN levels, decreases inflammation state, analyzed through sensitive C-reactive protein, and ameliorates lipid profile." (PMID 33171610, 2020). "Treatments with synthetic apelin peptides or nutritional strategies aimed at improving the APLN/APJ system may represent an important therapeutic option for cardiovascular disease." (PMID 33171610, 2020).